RBMX (RNA binding motif protein X-linked)
Diseases named in the same sentence as RBMX in open-access papers (continued):
Sharing a sentence is not in itself a finding about the gene and the disease.
infection (4 papers, 2020 to 2025). The state of being infected such as from the introduction of a foreign agent such as serum, vaccine, antigenic substance or organism. "Curiously, depletion of RBMX strongly increased the replicon replication but decreased the accumulation of 2C upon infection." (PMID 36306280, 2022). "RBMX inhibits the infection of human papillomavirus type 16 by preventing the inclusion of exon on HPV16 late L1 mRNAs for splicing." (PMID 32317327, 2020). "Taken together, in this study, we have identified a novel role of RBMX for suppressing HIV-1 transcription and infection." (PMID 32317327, 2020). "Intriguingly, ATL2/RBMX interaction was detected only in DENV-infected cells, suggesting that it is induced by the infection and might play a similar role as the one of IGF2BP2/ATL2 in case of DENV." (PMID 39565347, 2024).
hematological diseases (1 paper, 2021). "Therefore, we investigated the protein expression of the RNA binding protein X (RBMX), which has been shown to be of great relevance in disease initiation and progression in hematological diseases in 53 T-NHL cases using conventional immunohistochemistry." (PMID 34638274, 2021).
RBMX also shares sentences with these, for which no sentence is quoted: acute myeloid leukemia (2 papers); cervical cancer (2); autism (1); bladder urothelial carcinoma (1); Cirrhosis (1); colonic cancer (1); diffuse large B-cell lymphoma (1); endocervical adenocarcinoma (1); Fanconi anemia (1); Flavivirus Infections (1); genetic disorders (1); head and neck cancer (1); intellectual disability syndrome (1); kidney cancer (1); lung squamous cell carcinoma (1); myeloma (1); neurodevelopmental disorder (1); neurological disorders (1); Obesity (1); preeclampsia (1); rectum adenocarcinoma (1); renal clear cell carcinoma (1); skin cancer (1); small cell lung carcinoma (1); spinal muscular atrophy (1); testicular germ cell tumor (1); thyroid cancer (1); thyroid tumor (1); uveal melanoma (1).